PKD2 (polycystin 2, transient receptor potential cation channel)
Diseases named in the same sentence as PKD2 in open-access papers (continued):
Sharing a sentence is not in itself a finding about the gene and the disease.
autosomal dominant polycystic kidney disease (continued). "Studies in humans have shown that 85–90% of Autosomal Dominant Polycystic Kidney Disease (ADPKD) (OMIM ID: 173900) is caused by mutations in PKD1 (Entrez Gene ID: 5310), with other cases caused by mutations in PKD2 (Entrez Gene ID: 5311)." (PMID 21818326, 2011). "Autosomal dominant polycystic kidney disease (ADPKD), primarily caused by mutations in the PKD1 or PKD2 gene, is among the most common hereditary kidney diseases worldwide and is associated with significant extrarenal manifestations, including cardiovascular disease." (PMID 40980664, 2025). "For instance, Autosomal Dominant Polycystic Kidney Disease (ADPKD) is primarily attributed to pathogenic variants in the PKD1 and PKD2 genes, while Marfan syndrome and Neurofibromatosis type 1 (NF1) are mainly associated with the FBN1 and NF1 genes, respectively." (PMID 41411243, 2025). "Besides embryonic left–right asymmetry and autosomal dominant polycystic kidney disease, PKD2 is also involved in the development of other organs in model organisms." (PMID 39451240, 2024). "Autosomal dominant polycystic kidney disease (ADPKD) stands as the most prevalent genetic cystic kidney disorder, with 85% of cases attributed to mutations in the PKD1 gene on chromosome 16 and 10% to mutations in the PKD2 gene on chromosome 4." (PMID 38592079, 2024). "RGLS4326 is specifically developed to inhibit the pathological functions of the miR-17 family in autosomal dominant polycystic kidney disease (ADPKD), one of the most frequent monogenic disorders, caused by mutations in the PKD1 or PKD2 gene and for which therapeutic options are limited." (PMID 38338746, 2024). "Additionally, it will be interesting to explore the effect of CK2A1 activity in the PKD2 open-gate probability under PKD2-related clinical conditions such as autosomal dominant polycystic kidney disease." (PMID 37523531, 2023). "Autosomal dominant polycystic kidney disease (ADPKD) is the most common form, afflicting approximately 1 in 1,000 people and is caused by mutations in the transmembrane proteins polycystin-1 (Pkd1) and polycystin-2 (Pkd2)." (PMID 35253003, 2022). "Autosomal dominant polycystic kidney disease (ADPKD) is the most common form of hereditary cystic kidney disease, affecting one in 1000–2500 individuals and is mainly caused by mutations in the PKD1 (78%) and PKD2 (15%) genes." (PMID 36362756, 2022). "The PKD2 gene (polycystic kidney disease 2) affects body weight in Australian Merino sheep." (PMID 33050182, 2020). "Digenic inheritance has also already been reported to have a prognostic role in other kidney diseases, such as congenital nephrotic syndrome (mutations in NPHS1 and NPHS2), autosomal dominant polycystic kidney disease (mutations in PKD1 and PKD2) and Bartter's syndrome." (PMID 33330536, 2020). "PKD2 and PKD1 genes are mutated in human autosomal dominant polycystic kidney disease." (PMID 29899465, 2018). "For example, PKD1 and PKD2 form complexes that are thought to sense urine flow and elicit downstream Ca2+ signals in the kidney; defects in this process may underlie autosomal dominant polycystic kidney disease (ADPKD)." (PMID 27272319, 2016). "Autosomal dominant polycystic kidney disease (ADPKD) is a common hereditary renal cystic disease with an incidence of approximately 1:1000, which is mainly caused by mutations of the PKD1 or PKD2 genes." (PMID 27460786, 2016). "Autosomal dominant polycystic kidney disease (ADPKD) is the most common form of cystic disease, with a frequency of 1 in 800 live births and is caused by mutations in the PKD1 gene on chromosome 16 or the PKD2 gene on chromosome 4." (PMID 18810502, 2010). "Autosomal dominant polycystic kidney disease (ADPKD) is one of the most common single-gene inherited disorders, primarily resulting from mutations in the PKD1 gene (approximately 85%) or the PKD2 gene (approximately 15%)." (PMID 40308771, 2025).
autosomal dominant polycystic kidney disease (continued). "Autosomal Dominant Polycystic Kidney Disease (ADPKD) is the most common inherited kidney disease, caused by pathogenic variants in PKD1, PKD2, or rarely other genes." (PMID 40783883, 2025). "Autosomal dominant polycystic kidney disease (ADPKD), a prevalent and potentially lethal monogenic disorder, is characterized by progressive renal cyst formation driven by mutations in PKD1 or PKD2, encoding polycystin-1 (PC1) and polycystin-2 (PC2), respectively." (PMID 41086943, 2025). "Autosomal Dominant Polycystic Kidney Disease (ADPKD) is a systemic ciliopathy resulting from loss-of-function mutations in the PKD1 and PKD2 genes, which encode polycystin-1 (PC1) and polycystin-2 (PC2), respectively." (PMID 40801635, 2025). "Autosomal dominant polycystic kidney disease (ADPKD) is caused primarily by pathogenic variants in the PKD1 and PKD2 genes." (PMID 39883360, 2025). "Autosomal dominant polycystic kidney disease (ADPKD) is caused by mutations in PKD1 or PKD2, which encode polycystin-1 (PC1) and polycystin-2 (PC2), respectively." (PMID 40763312, 2025). "Autosomal dominant polycystic kidney disease (ADPKD) is the more prevalent form, subdivided into the PKD1 and PKD2 variants." (PMID 40710847, 2025). "Autosomal dominant polycystic kidney disease (ADPKD) is the most common monogenic inherited nephropathy, caused by mutations in either the PKD1 or PKD2 gene, which encode polycystin-1 and polycystin-2, respectively." (PMID 41195291, 2025). "Autosomal Dominant Polycystic Kidney Disease (ADPKD) is the most common genetic kidney disorder, predominantly caused by pathogenic variants in the PKD1 and PKD2 genes." (PMID 40268755, 2025). "To investigate whether the cysts were formed due to uncontrolled proliferation, as it is seen in autosomal dominant polycystic kidney disease with mutations PKD1 and PKD2 genes, we assessed Ki67 staining in the epithelial cells of proximal and distal tubules and found no significant changes." (PMID 39417621, 2024). "Patients with autosomal dominant polycystic kidney disease (ADPKD), a genetic disease due to mutations of the PKD1 or PKD2 gene, show signs of complement activation in the urine and cystic fluid, but their pathogenic role in cystogenesis is unclear." (PMID 38912583, 2024). "Autosomal dominant polycystic kidney disease (ADPKD) is the most common hereditary renal disease, and it is typically caused by PKD1 and PKD2 heterozygous variants." (PMID 37628640, 2023). "Indeed Pkd2 (Polycystic kidney disease 2), pyx (pyrexia), and pain (painless) genes involved in hygroreception, a sense that allows the flies to detect changing levels of moisture in the air, were found to be differentially expressed in tolerant strains under basal conditions." (PMID 36797754, 2023). "Autosomal dominant polycystic kidney disease (ADPKD), caused predominantly by mutations to PKD1 or PKD2, is the most common monogenic kidney disease." (PMID 37345660, 2023). "Autosomal dominant polycystic kidney disease (ADPKD) is one of the most common human monogenic diseases and is mainly caused by mutations in PKD1 or PKD2." (PMID 38066436, 2023). "Autosomal dominant polycystic kidney disease (ADPKD) is the most common hereditary kidney disease, affecting approximately 1:800 individuals; it is mainly due to mutations in two genes: PKD1 and PKD2." (PMID 37681898, 2023). "Mutations in PKD2 and PKD1 cause autosomal dominant polycystic kidney disease (ADPKD), a relatively common genetic nephropathy, wherein tubular epithelial cells proliferate to form cysts, ultimately resulting in renal failure." (PMID 38283366, 2023). "Autosomal dominant polycystic kidney disease (ADPKD): ADPKD is the most common inherited progressive renal disease caused by the mutation of two major genes, PKD1 and PKD2, and the rare genes, GANAB and DNAJB11." (PMID 37445416, 2023).
autosomal dominant polycystic kidney disease (continued). "Autosomal dominant polycystic kidney disease (ADPKD) is the most common monogenic-inherited kidney disease, caused primarily by mutations in either PKD1 (85%) or PKD2 (15%), with an estimated incidence of ~1 in 1000." (PMID 36766548, 2023). "Autosomal dominant polycystic kidney disease (ADPKD), one of the most common genetic diseases in humans, is caused by mutations in either PKD1 or PKD2, two genes encoding polycystin-1 (PC1) and polycystin-2 (PC2, or TRPP2) protein, respectively." (PMID 37028763, 2023). "Autosomal dominant polycystic kidney disease (ADPKD) is an inherited kidney disease caused by mutations in genes PKD1 and PKD2 encoding for proteins polycystin-1 (PC-1) and polycystin-2 (PC-2)." (PMID 36712680, 2022). "Autosomal dominant polycystic kidney disease (ADPKD) is the commonest life-threatening hereditary disease, most of which is caused by a mutation in either the PKD1 or PKD2 gene." (PMID 35159216, 2022). "Autosomal dominant polycystic kidney disease (ADPKD) is an inherited kidney disease caused by mutations in polycystic kidney disease 1 gene (PKD1) and/or PKD2, whereby PKD1 mutations lead to the most severe ADPKD manifestations." (PMID 36614108, 2022). "Mutations in pkd1 or pkd2, which encode PC1 and PC2 respectively, result in autosomal dominant polycystic kidney disease (ADPKD), which is one of the most common cilia-related pathologies." (PMID 33919210, 2021). "Autosomal Dominant Polycystic Kidney Disease (ADPKD) is a major renal pathology provoked by the deletion of PKD1 or PKD2 genes leading to local renal tubule dilation followed by the formation of numerous cysts, ending up with renal failure in adulthood." (PMID 34124016, 2021). "Autosomal dominant polycystic kidney disease (ADPKD) is associated with mutations in PKD1 and PKD2, changes in apical actin and cilia dysfunction." (PMID 34250905, 2021). "Autosomal dominant polycystic kidney disease (ADPKD) is the leading genetic disease associated with end-stage renal disease and is caused by loss-of-function mutations in either PKD1 or PKD2." (PMID 34733559, 2021). "Autosomal Dominant Polycystic Kidney Disease (ADPKD) is one of the most common causes of end-stage renal failure, caused by mutations in PKD1 or PKD2 genes." (PMID 31879244, 2020). "Autosomal dominant polycystic kidney disease (ADPKD), the predominant type of inherited kidney disorder, occurs due to PKD1 and PKD2 gene mutations." (PMID 32957937, 2020). "Autosomal dominant polycystic kidney disease (ADPKD) is the most common (1:1000) adult-onset genetic chronic kidney disease (CKD) caused by variants in either PKD1, PKD2 or, rarely, other genes." (PMID 33147804, 2020). "Autosomal dominant polycystic kidney disease (ADPKD), a common of monogenetic disorder caused by the polycystic kidney disease-1 (PKD1) or PKD2 genes deficiency." (PMID 31907669, 2020). "Autosomal Dominant Polycystic Kidney Disease (ADPKD) typically results from a mutation in the PKD1 and PKD2 genes, which code for polycystin-1 (PC1) and polycystin-2 (PC2), respectively." (PMID 30792735, 2019). "Autosomal dominant polycystic kidney disease (ADPKD), caused by mutations in either PKD1 or PKD2, is one of the most common monogenetic disorders and the leading genetic cause of end-stage renal disease (ESRD) in the United States1–3." (PMID 30760828, 2019). "The main mutational genes causing autosomal dominant polycystic kidney disease (ADPKD) are PKD1 and PKD2 as well as some rare pathogenic genes." (PMID 31056860, 2019). "Autosomal dominant Polycystic Kidney Disease (ADPKD) is a monogenic disorder, caused by loss-of-function mutations in either the PKD1 (in ∼85% of cases) or PKD2 (in the remaining ∼15%) genes." (PMID 30480096, 2018). "Here, we analyse the spatial organization of a large region spanning the polycystic kidney disease 2 (PKD2) gene, one of the genes responsible of autosomal dominant polycystic kidney disease (ADPKD)." (PMID 29986647, 2018).
autosomal dominant polycystic kidney disease (continued). "Autosomal dominant polycystic kidney disease (ADPKD) is an incurable inherited chronic disorder characterized by progressive kidney enlargement and frequent end-stage renal disease due to numerous fluid-filled cysts that are induced by mutations and loss of heterozygosity in PKD1 or PKD2 genes." (PMID 29995892, 2018). "Autosomal dominant polycystic kidney disease (ADPKD) is caused by mutations in PKD1 or PKD2 which encodes polycystin-1 (PC1) and polycystin-2, respectively." (PMID 28904368, 2017). "Molecular diagnostics of autosomal dominant polycystic kidney disease (ADPKD), which is the most common inherited kidney disease, relies on mutation screening of PKD1 (16p13.3; OMIM ID: 601313) and PKD2 (4q21; OMIM ID: 173910)." (PMID 28604601, 2017). "The clue that cilia could be involved not only in the generation but also the sensation of nodal flow came from the genetic analysis of mice mutant for Pkd2, a Ca2+ permeable ion channel involved in the pathogenesis of autosomal dominant polycystic kidney disease (ADPKD) in man." (PMID 23720541, 2013). "In the case of autosomal dominant polycystic kidney disease (ADPKD), CRISPR was used to delete the PKD2 gene, facilitating a deeper understanding of the disease’s pathogenesis." (PMID 39595570, 2024). "Autosomal dominant polycystic kidney disease (ADPKD) is a genetic disorder, which is caused by mutations in the PKD1 and PKD2 genes, characterizing by progressive growth of multiple cysts in the kidneys, eventually leading to end-stage kidney disease (ESKD) and requiring renal replacement therapy." (PMID 35847973, 2022). "Autosomal dominant polycystic kidney disease (ADPKD) is the most common genetic disorder of the kidney, caused by mutations in the PKD1 and PKD2 genes that encode for transmembrane proteins polycystin-1 (PC1) and polycystin-2 (PC2), respectively." (PMID 35847973, 2022). "Autosomal dominant polycystic kidney disease (ADPKD) is due to germ-line variants, predominantly in either PKD1 (85%) or PKD2 (15%), encoding the polytopic integral membrane, polycystin-1, and the calcium transient receptor channel, polycystin-2, respectively." (PMID 34638853, 2021). "Formation of renal cysts is the hallmark of autosomal dominant polycystic kidney disease (ADPKD), which is the most common ciliopathy and is mainly caused by mutations in the genes PKD1 and PKD2, which encode the proteins polycystin-1 (PC1) and polycystin-2 (PC2)." (PMID 31979260, 2020). "Autosomal dominant polycystic kidney disease (ADPKD) is caused by mutations in PKD1 or PKD2 gene, encoding the polycystic kidney disease protein polycystin‐1 and the transient receptor potential channel polycystin‐2 (also known as TRPP2), respectively." (PMID 31441214, 2019). "Autosomal dominant polycystic kidney disease (ADPKD) is an inherited monogenic renal disease characterised by the accumulation of clusters of fluid-filled cysts in the kidneys and is caused by mutations in PKD1 or PKD2 genes." (PMID 30858458, 2019). "Amo is a homolog of the humantransient receptor potential channel TRPP2 (also known as PKD2), which ismutated in autosomal dominant polycystic kidney disease." (PMID 21625494, 2011). "Two males were incidentally diagnosed with AS through genetic testing during screening for autosomal dominant polycystic kidney disease, with no pathogenic variants found in the PKD1 or PKD2 genes." (PMID 40806767, 2025). "Polycystin 2 (PKD2) is a non-selective transient receptor potential (TRP) cation channel, which, when mutated or absent, leads to 15% of Autosomal Dominant Polycystic Kidney Disease (ADPKD) cases." (PMID 34680887, 2021). "Autosomal dominant polycystic kidney disease (ADPKD; OMIM *601313 for PKD1, and *173910 for PKD2) is the most common hereditary kidney disease, predominantly characterized by the presence of cysts in both kidneys leading to end-stage renal disease (ESRD), usually in adulthood." (PMID 29973168, 2018).
autosomal dominant polycystic kidney disease (continued). "In humans, PKD2 is a critical Transient Receptor Potential Polycystin family (TRPP) channel that, if defective, will lead to autosomal dominant polycystic kidney disease (ADPKD)." (PMID 26230712, 2015).